PIK3CA (phosphatidylinositol-4,5-bisphosphate 3-kinase catalytic subunit alpha)
Diseases named in the same sentence as PIK3CA in open-access papers (continued):
Sharing a sentence is not in itself a finding about the gene and the disease.
colon carcinoma (continued). "Right-sided colon cancers had higher rates of microsatellite instability, more frequent aberrant activation of the EGFR pathway including higher BRAF and PIK3CA mutation rates, and increased mutational burden compared to left-sided colon and rectal cancers." (PMID 29156800, 2017). "We next assessed the percentage of cells in each phase of the cell cycle within these PIK3CA mutant and wild-type colon cancer cells." (PMID 29152088, 2017). "The dose-response curves of PIK3CA-mutant and PIK3CA-wild-type colon cancer cell lines were generated and the half maximal inhibitory concentration (IC50) values of each PIK3CA subgroup were compared." (PMID 29152088, 2017). "This study aims to characterize colon cancer with regard to KRAS, BRAF, and PIK3CA mutations, microsatellite instability (MSI), and average DNA copy number, in connection with tumour dissemination and recurrence in patients with colon cancer." (PMID 25884297, 2015). "Contrary to resistance against EGFR and ERBB2 targeting, the genetic inhibition of ERBB3 results in anti-tumorigenic in HCT116 colon cancer cells harboring constitutively active KRAS and PIK3CA mutations." (PMID 24970817, 2014). "We observed many KRAS (52.9%), PIK3CA (12.4%), and NRAS (7.4%) mutations in a colon cancer tissue collection (N = 121)." (PMID 24658394, 2014). "In our study, 80% of the PDX models were genomically concordant with the primary colon tumors, and 1 PDX model (ID 30306113) demonstrated a newly emerged PIK3CA oncogenic mutation (E542K) with allelic frequency of 49%." (PMID 25526474, 2014). "Regarding the primary location, 64.8% of KRAS mutations (p=0.07) and 58% of PIK3CA mutations (p=0.036) occurred in left-sided colorectal tumours, whereas four (66.7%) of BRAF mutations in right-sided colon carcinomas (p=0.024)." (PMID 23374602, 2013). "Here, we demonstrate that the treatment of FC PIK3ca* mice with the mTOR inhibitor, rapamycin, results in a dramatic response in advanced colon cancers." (PMID 23593290, 2013). "In a study of colon cancer xenografts, there was concordance between gene copy number and mutation (NRAS, KRAS, BRAF, PIK3CA) in first- and second-generation xenografts and in the parent tumor." (PMID 23981300, 2013). "Recently, we developed a novel mouse model of colon cancer in which tumors are initiated by a dominant active PI3K (FC PIK3ca*)." (PMID 23593290, 2013). "While several investigators have examined the effects of these mutations in cell lines, our laboratory recently developed a murine model of colon cancer that is initiated by a dominant active PI3K (FC PIK3ca*)." (PMID 23593290, 2013). "The second was a colon cancer cell line HCT116, which is heterozygous for the H1047R PIK3CA mutation, PI3Kα (H1047R/+), paired with cells in which the mutant allele has been knocked-out to render the cells functionally WT, PI3Kα (+/−)." (PMID 23028762, 2012). "The clinical response observed in the colon cancer patient with coexistent KRAS and PIK3CA mutations contrasts with the preclinical finding in which such coexpression generally conferred resistance to BYL719." (PMID 23232172, 2012). "Dominant activating mutations of PIK3CA, encoding P110α, have been identified in a variety of tumor types, including GBM, breast, and colon cancer, and have been shown to promote activation of P110α despite the presence of the P85 negative regulatory subunit." (PMID 23166678, 2012).
colon carcinoma (continued). "Direct sequencing of the hot spot regions at exons 9 and 20 of Pik3ca in the colonic tumors validated our GEM model as a surrogate for PIK3CA wild-type CRC, which we used in our in vivo NVP-BEZ235 treatment studies." (PMID 21966435, 2011). "Taken together, these results demonstrate that in vivo treatment with NVP-BEZ235 results in significant regression in PIK3CA wild-type colonic tumors." (PMID 21966435, 2011). "OncoCarta assays interrogate 99%, 98%, and 78% of the known colon cancer mutations in BRAF, KRAS, and PIK3CA, respectively, based on a large number of colon cancer samples that have been sequenced in BRAF (n = 4628), KRAS (n = 858) and PIK3CA (n = 247)." (PMID 20233444, 2010). "The colon cancer cell line HCT116, in addition to KRAS mutation, also harbors an activating mutation in the RAS effector PIK3CA." (PMID 19492075, 2009). "A recent study also showed that PIK3CA mutant colon cancer cell lines have increased metastatic potential in an orthotopic model." (PMID 19384426, 2007). "Following in vivo infusions of [13C5]-glutamine in mice bearing subcutaneous colon cancer xenografts, we further verified that labeling from glutamine to most tricarboxylic acid cycle intermediates was higher in PIK3CA-mutant subcutaneous xenograft tumors than in wild-type PIK3CA tumors." (PMID 39717717, 2025). "Moreover, in several other cancer related studies, the frequency of PIK3CA was reported as high in endometrial (36%), head/neck squamous cell carcinoma (33%), and colon cancer (32%)." (PMID 37821962, 2023). "Colon cancer cells with or without PIK3CA mutation and with or without circLHFPL2 overexpression were treated with MEK inhibitors AZD6244 or RDEA119 for 24 h." (PMID 35619132, 2022). "Compared to the HCT116 and DLD1 PIK3CA-mutant cells, the cell viability of the WT cells was greatly reduced upon treatment with AZD6244 or RDEA119, indicating that PIK3CA mutation enhanced drug resistance of colon cancer cells." (PMID 35619132, 2022). "Notably, we observed that mutations in KRAS, PIK3CA, CREBBP, FAT1, PKHD1, ARID2, and POLE were specifically enriched in right-site colon cancers in both our cohort and the validation cohort." (PMID 36439454, 2022). "HT 29 and Caco-2 cells are PIK3CA wild-type colon cancer cells." (PMID 34360807, 2021). "Another cell line had PIK3CA I391M variant, a variant previously identified in colon cancer but shown not to increase catalytic activity." (PMID 33549048, 2021). "Caco-2 cells are KRAS wild-type and PIK3CA wild-type colon cancer cells." (PMID 34360807, 2021). "We also found that p70S6K1 activation by IGF-1R inhibition is independent of K-Ras and PIK3CA mutations that frequently occur in colon cancer." (PMID 32843616, 2020). "Furthermore, inhibition of MEK promoted tumour regression in colon cancer patient-derived xenograft models expressing PIK3CA wt." (PMID 30944457, 2019). "In addition, decreased cell death was observed in SW1116 colon cancer cells, which express wild-type PIK3CA, transfected with β-catenin cDNA." (PMID 30944457, 2019).
colon carcinoma (continued). "Therefore, our results demonstrated that NVP-TNKS656 is able to overcome MEK inhibitor resistance in KRAS mutant and PIK3CA mt/β-catenin wt colon cancer cells." (PMID 30944457, 2019). "DLD-1 and HCT-8 cells, two colon cancer cell lines with mutant PIK3CA expression, were selected." (PMID 30944457, 2019). "Additionally, cell death increased significantly after MEK inhibitor exposure in β-catenin siRNA-treated HCT-8 cells, which are PIK3CA mutant colon cancer cell lines." (PMID 30944457, 2019). "We propose that inhibition of the WNT pathway, particularly β-catenin, may bypass resistance to MEK inhibition in human PIK3CA mt colon cancer." (PMID 30944457, 2019). "We tested the MEK inhibitor in PIK3CA wild(wt) and mutant(mt) colon cancer cells." (PMID 30944457, 2019). "Furthermore, PIK3CA mutant colon cancer cells are reported to upregulate ALT2 expression, and inhibition of ALT2 activity decreases the growth of PI3KCA mutant tumors." (PMID 30609754, 2019). "We conducted in vitro experiments to test our hypothesis that the anti-proliferative activity of aspirin might be stronger for PIK3CA-mutant colon cancer cells than for PIK3CA-wild-type colon cancer cells." (PMID 29152088, 2017). "Another drawback is that our current study did not utilize functional assays to investigate potential molecular mechanisms through which aspirin may exert stronger anti-cancer effects on PIK3CA-mutant colon cancer cells than PIK3CA-wild-type cells." (PMID 29152088, 2017). "Previous retrospective analyses investigating aspirin use in colon cancers according to PIK3CA mutation status did not specify which PIK3CA mutations were included." (PMID 29152088, 2017). "The colon cancer cell lines RKO and HCT-116 harbor mutated PIK3CA." (PMID 26918349, 2016). "Our data presented here demonstrated that PIK3CA (E545K) mutation was significantly associated with tumor recurrence in stage III, besides, E545K also played as an independent prognostic gene biomarker for adverse outcomes in stage III colon cancer alone." (PMID 27074743, 2016). "Our data in colon cancer showed that the majority of mutations identified were shared between a primary tumor and its cognate paired metastatic lesion, including KRAS, APC, and PIK3CA which are commonly tested mutations in our patients." (PMID 25974029, 2015). "The aim of this multicenter study was to investigate the prognostic value of PIK3CA mutations in nonmetastatic colon cancer (CC) according to MSI status." (PMID 25641861, 2015). "The frequency of PIK3CA E542K mutation (COSM760) in primary colon tumor (ID 30306113) did not harbor this mutation." (PMID 25526474, 2014). "Fifteen genes (DUSP2, INFGR1, IL6, IRF2, JAK2, MAP3K10, MMP1, NFkB1A, NOS2A, PIK3CA, SEPX1, SMAD3, TLR2, TYK2, and VDR) were associated with colon cancer mortality (PARTP <0.05); JAK2 (PARTP = 0.0086), PIK3CA (PARTP = 0.0098), and SMAD3 (PARTP = 0.0059) had the strongest associations." (PMID 25541970, 2014). "Fifteen genes (DUSP2, INFGR1, IL6, IRF2, JAK2, MAP3K10, MMP1, NFkB1A, NOS2A, PIK3CA, SEPX1, SMAD3, TLR2, TYK2, and VDR) were significantly associated with colon cancer mortality at the <0.05 level; an additional 15 genes had gene PARTP values between 0.05 and 0.10." (PMID 25541970, 2014). "Human colonic tumors contain several possible oncogenic driver mutations which could potentially be targeted, including KRAS, BRAF, and PIK3CA These mutant kinases have been key targets for the continued development of therapeutic agents." (PMID 23593290, 2013).
colon carcinoma (continued). "Interestingly, ∼45% of PIK3R1-mutant colon cancer specimens and ∼22% of PIK3R1-mutant endometrioid endometrial cancers also carried mutations of PIK3CA." (PMID 23166678, 2012). "In addition to known oncogenic mutations in PIK3CA, recent cancer genome sequencing efforts have identified recurrent somatic mutations of PIK3R1 in GBM, endometrial, and colon cancers." (PMID 23166678, 2012). "PIK3CA status of breast and colon cancer cell lines investigated for glucose dependency." (PMID 23028762, 2012). "In addition, knockdown of either PIK3CA or SLC6A6 resulted in decreased expression of α-SMA and increased expression of E-cadherin along with decreases in CD44, CD133, and Nanog, indicating a loss in markers for EMT and colon cancer stem cells." (PMID 34571860, 2021). "In addition, caspase-3 cleavage was observed in colon cancer cells that express wild-type PIK3CA." (PMID 30944457, 2019). "Thus, differences in sensitivity to MEK inhibitors may depend on the PIK3CA genotype in human colon cancer cells." (PMID 30944457, 2019). "Therefore, we hypothesized that the anti-cancer effects of aspirin might be stronger for PIK3CA-mutant colon carcinoma cell lines than for PIK3CA-wild-type colon carcinoma cell lines." (PMID 29152088, 2017). "However, whether aspirin directly influences the viability of PIK3CA-mutant colon cancer cells is poorly understood." (PMID 29152088, 2017). "Notably, right-sided colon cancers comprised nearly half (48.0%) of tumors with PIK3CA alterations." (PMID 28178681, 2017). "The higher rate of activating PIK3CA mutations and PTEN loss in left- and right-sided colon cancers compared to rectal cancers could contribute to a lower response to anti-EGFR therapies in some colon cancers and supports the use of alternative treatments." (PMID 29156800, 2017). "However, whether mutations in KRAS together with downstream factors BRAF, PIK3CA and NRAS impact prognosis is still unclear for stage II-III colon cancer." (PMID 27074743, 2016). "Moreover, PIK3CA (E545K) mutation was significantly associated with tumor recurrence (P = 0.031) and acted independently prognostic for poor OS (P = 0.044), while only in stage III colon cancer." (PMID 27074743, 2016). "Given that gene mutations (KRAS, BRAF and PIK3CA) influence cetuximab sensitivity, we chose two cell lines (Caco-2 and DiFi) that express wild-type KRAS, BRAF and PIK3CA, paralleling the molecular features of colon cancer patients who are most likely to respond to cetuximab." (PMID 24714091, 2014). "Also, recently a study of colon cancer patients showed that PIK3CA mutations did not confer any significant effect on mortality among patients with KRAS-mutated tumors and is consistent with our findings on tumors growth in HCT116 cells." (PMID 19492075, 2009). "To confirm the successful induction of the 6 model genes (SIRT3, PIK3CA, ITGA3, DAPK1, PAK1, and CASP3), we gathered a set of 39 colon cancer tissue samples." (PMID 38213716, 2024). "To test if the drug combination induced NETs in immune-competent mouse tumor models, we generated Pik3ca E545K oncogenic mutant knockin CMT93 and MC38 mouse colon cancer cell lines using CRISPR-mediated genome editing." (PMID 38194275, 2024). "To identify potential strategies for further application in the clinic, we compared the IC50 of several PIK3CA inhibitors and the endogenous levels of RAB3C and dystrophin in the colon cancer cell panel." (PMID 36652260, 2023).
colon carcinoma (continued). "Given that oxaliplatin is also a standard chemotherapeutic agent used in colon cancer treatment, we also examined the expression of molecular signature genes PIK3CA, SLC6A6, ASAP-1 and TMEM-43 in colon cancer cells resistant to this drug." (PMID 34571860, 2021). "From the literature survey, we found that TPK1 is an oncogene for colon cancer, and three genes (PTEN, GNPDA1 and PIK3CA) appear in head and neck cancer." (PMID 32269785, 2020). "β-Catenin knockdown led to increased levels of cell death in the colon cancer cell line DLD-1, which expresses mutant PIK3CA, in the presence of an MEK inhibitor." (PMID 30944457, 2019). "In this retrospective study, we evaluated common hot spot gene mutations located downstream of EGFR signaling pathway, the potential prognostic value for KRAS, BRAF, PIK3CA and NRAS was assessed in 228 stage II-III colon cancer." (PMID 27074743, 2016). "Even more recently another study examined the effect of cetuximab on several colon cancer cell lines and found that PTEN null, PIK3CA mutant and Ras/BRAF mutants cell lines are resistant to cetuximab." (PMID 18700047, 2008). "Their clinical relevance in gastric and colon cancers stems from their frequent dysregulation, often driven by genetic alterations (e.g., KRAS, BRAF, PIK3CA, PTEN, and mTOR), which leads to constitutive activation and fosters uncontrolled cancer cell growth and survival." (PMID 40729043, 2025). "On the contrary, the five remaining colon cancer cell lines, namely SW48, DIFI, MICOL24, CACO-2 and E705, showed no hyperactivating mutations in KRAS, NRAS, BRAF and PIK3CA genes, with the E705 cell line carrying a silent mutation in PIK3CA gene." (PMID 33233823, 2020). "Nevertheless, although they did not distinct rectal from left colon cancers in the comparative analysis, differences in PIK3CA and KRAS are correlative with ours, except the high proportion of KRAS also seen in rectal location within our population." (PMID 29632645, 2018). "Similarly, five genes including TOP2A, REL, SHH, ROS1, and CHEK2 in colon cancer gene network and three genes including RBL1, MAPK9, and PIK3CA in adenocarcinoma of lung gene network are selected." (PMID 29670664, 2018). "Initially, we examined the effect of a variety of aspirin doses (0, 0.5, 1, 2, 4, 6, 8, 10, and 12 mM) on cell proliferation after exposure to aspirin for 12 to 96 hours in two PIK3CA-mutant (HCT15 and HCT116) and PIK3CA-wild-type (SW480 and SW620) colon cancer cell lines." (PMID 29152088, 2017). "In the present study, the effect of KRAS/BRAF/PIK3CA oncogenic pathways on the autophagic cell properties and on main components of the autophagic machinery like p62 (SQSTM1), Beclin-1 (BECN1) and MAP1LC3 (LC3) in colon cancer cells was investigated." (PMID 26802026, 2016). "To test whether PIK3CA, SLC6A6, TMEM-43, and ASAP-1 expression is driven by CLDN1 and CLDN7 expression, we analyzed these genes and proteins in CLDN1-overexpressing SW480 (SW480CLDN1) and CLDN7-knockdown DLD-1 (DLDCLDN7KD) colon cancer cell lines." (PMID 34571860, 2021).